GDNF (glial cell derived neurotrophic factor)
Diseases named in the same sentence as GDNF in open-access papers (continued):
Sharing a sentence is not in itself a finding about the gene and the disease.
sleep disorder (2 papers, 2023 to 2025). A change from the patient's baseline sleeping pattern, in the hours slept and/or an alteration/dysfunction in the stages of sleep. "We found low levels of adenosine and GDNF were risk factors for PD with sleep disorders in this study." (PMID 36831743, 2023). "The correlation between serum levels of adenosine, GDNF, and associated neurotransmitters and sleep disorders was explored using logistic regression." (PMID 36831743, 2023). "Adenosine combined with GDNF had a higher diagnostic efficiency in predicting PD with sleep disorders by ROC analysis." (PMID 36831743, 2023). "To address this limitation, we analyzed the associations of adenosine, GDNF, and related neurotransmitters and PD with sleep disorders." (PMID 36831743, 2023). "This study aimed to detect the serum levels of adenosine, GDNF, and associated neurotransmitters and explored their correlations with PD with sleep disorders." (PMID 36831743, 2023). "Lower concentrations of GDNF and adenosine were associated with more serious sleep disorders." (PMID 36831743, 2023). "Adenosine combined with GDNF showed high diagnostic efficacy for PD with sleep disorders." (PMID 36831743, 2023). "This study revealed low adenosine and GDNF levels may be risk factors for sleep disorders in PD." (PMID 36831743, 2023). "Logistic regression analysis showed adenosine and GDNF were protective factors for preventing sleep disorders." (PMID 36831743, 2023). "Decreased GDNF in PD patients with sleep disorders can affect the regulation of these neurotransmitters, thereby worsening sleep disorders." (PMID 36831743, 2023). "For predicting sleep disorders, the GDNF, ADO, and ADO + GDNF areas under the curve were 0.815, 0.780, and 0.883 respectively (p < 0.001)." (PMID 36831743, 2023). "The threshold of GDNF in predicting sleep disorders was 305.205, with a sensitivity of 62.7% and a specificity of 91.7%." (PMID 36831743, 2023). "Using logistic regression analysis, we found that GDNF and adenosine were protective factors in PD patients with sleep disorders." (PMID 36831743, 2023). "Studying the interactions between adenosine, GDNF, and related neurotransmitters may provide better therapeutic strategies for sleep disturbances and a novel understanding of the pathogenesis of PD with sleep disorders." (PMID 36831743, 2023). "A study has detected serum levels of adenosine, glial-derived neurotrophic factor (GDNF), and GABA, and used logistic regression to explore the correlation between these factors and sleep disorders." (PMID 40046435, 2025). "Binary logistic regression was set up with the presence of sleep disorders in PD patients as the dependent variable (yes = 1, no = 0), and GDNF, ADO, GABA, HAMD, HAMA, UPDRS-III, and H-Y stage as the independent variable." (PMID 36831743, 2023). "However, elucidation of the role of GDNF in sleep is limited to basic research as no clinical studies have been conducted to test GDNF levels in PD patients with sleep disorders." (PMID 36831743, 2023).
steatosis (2 papers, 2020 to 2022). Increased lipid within the cytoplasm of cells. "Thus, GDNF may be a therapeutic agent in reversing steatosis and steatohepatitis." (PMID 32175323, 2020).
α-synucleinopathies (2 papers, 2021 to 2022). "Nevertheless, the remaining RET expression in the nigral neurons is enough to activate the downstream molecule p-rpS6, and the synucleinopathy is not an impediment for GDNF to express its trophic effect." (PMID 34769132, 2021). "Future research on GDNF should be carried out in the stereotaxic BSSG model of PD, where GDNF effects can be evaluated on neuroinflammation, DA neurodegeneration, α-synucleinopathy, and motor and non-motor deficits." (PMID 34769132, 2021).
adenoma (1 paper, 2025). A neoplasm arising from the epithelium. "Several interactions only occurred in specific locations, such as signalling pathways of CALCR, RANKL and TWEAK in the submucosa, GDNF, GDF, IL12, CD30 and CD137 signalling pathways in the adenoma, and PD‐L1, GP1BA, RESISTIN and SPP1 signalling pathways in tumour." (PMID 39934971, 2025).
adenovirus infection (1 paper, 2013). "To verify this assumption, we created VMs and iPSCMs overexpressing GDNF by adenovirus infection (AdGDNF-VMs, iPSCMs)." (PMID 23843937, 2013).
alcohol abuse (1 paper, 2025). The use of alcoholic beverages to excess, either on individual occasions ("binge drinking") or as a regular practice. "The involvement of GDNF in regulating dopaminergic neuronal plasticity has shown promise in influencing the biochemical adaptation processes and the rewarding effects associated with drug addiction, suggesting its potential application in the treatment of substance or alcohol abuse." (PMID 40642294, 2025).
allergic asthma (1 paper, 2026). A asthma with a basis in a pathological type I hypersensitivity reaction. "We suggest that GDNF-RET signaling promotes PNEC hyperplasia and that the PNEC-CGRP-ILC2 axis is closely associated with the development of allergic asthma, presenting a possible new treatment strategy." (PMID 41968620, 2026).
Anorexia (1 paper, 2020). Lack of desire to eat (loss of appetite). "Mechanistically, induction of anorexia via the brainstem-restricted GDF-15 receptor GFRAL (glial cell-derived neurotrophic factor [GDNF] family receptor α-like) is well-documented." (PMID 32508832, 2020).
anxiety disorder (1 paper, 2024). A category of psychiatric disorders which are characterized by anxious feelings or fear often accompanied by physical symptoms associated with anxiety. "Nevertheless, GDNF does not appear as a predictor for treatment remission in other psychiatric disorders, such as general anxiety disorder." (PMID 38362105, 2024).
Arrhythmia (1 paper, 2013). Any cardiac rhythm other than the normal sinus rhythm. "In this study, we used GDNF to increase sympathetic innervation in transplanted cardiomyocyte sheets, and it may induce arrhythmias." (PMID 24066291, 2013).
atopic eczema (1 paper, 2022). A common chronic pruritic inflammatory skin disease with a strong genetic component. "Keratinocytes are also capable of secreting NGF and glial cell-line-derived neurotrophic factor (GDNF) to induce neurite outgrowth and increase CGRP + sensory fibers, increasing nerve fiber density in the epidermis of patients with atopic eczema." (PMID 35646918, 2022).
behavioral addiction (1 paper, 2019). "This study further confirms the role of GDNF in addiction, while it is the first study to show the association of GDNF polymorphism with gambling as a type of behavioral addiction." (PMID 31446765, 2019). "Our results confirm the role of GDNF in addiction, and to our knowledge, this is the first study to show association of GDNF gene polymorphisms with gambling as a type of behavioral addiction." (PMID 31446765, 2019).
Brain atrophy (1 paper, 2024). Partial or complete wasting (loss) of brain tissue that was once present. "Therefore, in CSF, GDNF level should be higher and more rapidly increasing in phenotypes with more severe brain atrophy and faster clinical deterioration." (PMID 38307947, 2024).
brain edema (1 paper, 2020). Increased intracellular or extracellular fluid in brain tissue. "Also, GDNF is one of the known factors in controlling brain edema." (PMID 33224215, 2020).
breast tumors (1 paper, 2018). "The abundance of GDNF mRNA appears to be extremely low in primary breast tumors analyzed by TCGA, which were in most cases collected before therapeutic intervention." (PMID 29608602, 2018). "To determine whether GDNF is an important contributor to primary breast tumors, we have conducted a detailed statistical analysis of publicly available data." (PMID 29608602, 2018).
cerebellar ataxia (1 paper, 2025). A neurological syndrome characterized by clumsy and uncoordinated movement of the limbs, trunk, and cranial muscles. "In this context, neurotrophic molecules such as GDNF, and IGF-1 have been shown to promote Purkinje cell survival and to delay neurodegeneration and motor deficits in animal models of hereditary cerebellar ataxia." (PMID 41226418, 2025).
Chagas disease (1 paper, 2013). A parasitic infection caused by Trypanosoma cruzi. "Upregulation of both NGF and GDNF was also demonstrated in rats with Trypanozoma cruzi infection (Chagas disease) causing sympathetic as well as parasympathetic denervation." (PMID 23843937, 2013). "The same group reported that in rats infected with Trypanosoma cruzi (Chagas disease) anti-GDNF gold particles in atrial granules increased transiently at the time of maximal autonomic denervation." (PMID 23843937, 2013).
cocaine addiction (1 paper, 2023). "This information is important in guiding future development of GDNF-RET system modulators for treating cocaine addiction." (PMID 37238631, 2023). "Together, these data indicate that a 70–80% reduction of GDNF in the NAc after the onset of cocaine addiction increases the rewarding effects of cocaine." (PMID 37238631, 2023). "Thus, RET antagonism in the VTA coupled with intact or enhanced accumbal GDNF function may provide a new approach towards cocaine addiction treatment." (PMID 37238631, 2023). "Taken together, our findings indicate that appropriate GDNF activity in NAc and dampened RET activity in the VTA facilitates recovery from cocaine addiction." (PMID 37238631, 2023). "This suggests that increased GDNF-RET signaling in the VTA enhances and the reduction in VTA RET levels reduces cocaine addiction." (PMID 37238631, 2023). "Here, through independent accumbal GDNF or VTA RET reduction after establishment of cocaine-induced conditioned place preference, we investigate this pathway’s potential to treat cocaine addiction." (PMID 37238631, 2023). "Thus, reducing GDNF in the NAc and RET levels in the VTA have opposing roles in cocaine addiction." (PMID 37238631, 2023). "This suggests a specific role of NAc GDNF and VTA RET signaling in cocaine addiction, but not cocaine-induced motor activity." (PMID 37238631, 2023).
colitis Crohn (1 paper, 2011). "Colonic parts without inflammation in patients with colitis Crohn showed a reduced labelling of GFAP and no expression of GDNF in comparison to non-inflamed gut structures of patients with UC." (PMID 21235736, 2011).
coloboma (1 paper, 2018). An abnormality in which a part of a structure in one or both eyes is missing. "To this end we compared RNA harvested from eyes of wild-type embryos and TGFβ2/GDNF double mutant embryos, in which the coloboma phenotype was assigned to TGFβ2 function." (PMID 29593116, 2018). "Notably, we found marked, severe coloboma phenotypes in both TGFβ2 KO as well as in TGFβ2/GDNF double KO conditions." (PMID 29593116, 2018). "Secondly, the marked, strong coloboma phenotypes can be observed in both TGFβ2−/− GDNF−/− and TGFβ2−/− GDNF+/+ embryos from a mixed breeding background, occasionally also presenting a dorsal coloboma, while the phenotype of TGFβ2 KO embryos from a sole breeding background is noticeably milder." (PMID 29593116, 2018). "Since we found such coloboma phenotypes in both TGFβ2 and TGFβ2/GDNF mutants, but not in GDNF mutants, we found it likely that the phenotype was resulting from a TGFβ2 loss." (PMID 29593116, 2018). "Even if GDNF single KO embryos do not show a coloboma and the transcriptional analyses performed during our analyses contradict, we cannot totally rule out that an affected GDNF signalling sensitizes the system to the loss of TGFβ2." (PMID 29593116, 2018). "TGBβ2-dependent coloboma was first observed in TGFβ2/GDNF double mutants (, Rahhal & Heermann 2009, unpublished observations) and subsequently in TGFβ2 single mutants, derived from the same breeding background (this study), but not in GDNF single mutants." (PMID 29593116, 2018).
congenital muscular dystrophy (1 paper, 2023). A muscular dystrophy that is characterized by diminished muscle tone (hypotonia), progressive muscle weakness and degeneration (atrophy), abnormally fixed joints, spinal rigidity, and delays in reaching motor milestones such as sitting or standing unassisted. "Furthermore, GDNF might also play a role in congenital muscular dystrophy (CMD)." (PMID 37251644, 2023).
deafness (1 paper, 2018). An inherited or acquired condition characterized by the complete loss of the ability to hear from one or both ears. "One experiment compared the ability of electrical stimulation and glial-derived neurotrophic factor (GDNF), alone and in combination, to enhance the survival of residual spiral ganglion neurons in a guinea pig model of deafness." (PMID 30274337, 2018).
diabetic neuropathy (1 paper, 2025). A chronic, pathological complication associated with diabetes mellitus, where nerve damages are incurred due to diabetic microvascular injury involving small blood vessels that supply these nerves, resulting in peripheral and/or autonomic nerve dysfunction. "In Alzheimer’s models, Brain-Derived Neurotrophic Factor (BDNF) enhances ATF6-mediated adaptive UPR, while, in diabetic neuropathy, Glial Cell Line-Derived Neurotrophic Factor (GDNF) suppresses PERK hyperactivation." (PMID 40722704, 2025).
disc degeneration (1 paper, 2025). "The upregulation of GDNF in degenerated disc tissues suggests its involvement in the pain mechanism associated with disc degeneration in this mouse model." (PMID 40012719, 2025).
embryonal carcinoma (1 paper, 2017). A non-seminomatous malignant germ cell tumor characterized by the presence of large germ cells with abundant cytoplasm resembling epithelial cells, geographic necrosis, high mitotic activity, and pseudoglandular and pseudopapillary structures formation. "As shown in a similar study by Baldassarre, GDNF induces the expression of the CDK inhibitor p27kip1, halting proliferation in the embryonal carcinoma cell line NT2/D1; this effect contrasts the physiological role of GDNF in germ cells." (PMID 28878618, 2017).
encephalitis (1 paper, 2022). An acute inflammatory process affecting the brain parenchyma. "Here, we found a significantly elevated level of GDNF in the CSF of WNV meningitis patients when compared to encephalitis patients." (PMID 35458486, 2022).
endometrial cancer (1 paper, 2025). Primary or metastatic malignant neoplasm involving the endometrium (mucous membrane that lines the endometrial cavity). "Kaplan Meier plots using TCGA Endometrial Cancer database revealed that high mRNA expression of SCGB1D2, CD52, GNG2, GDNF, and SCUBE1correlated with favorable prognosis in EC patients (n=547)." (PMID 41262902, 2025).
Exotropia (1 paper, 2020). A form of strabismus with one or both eyes deviated outward. "Even 3 months after GDNF treatment ended, the monkeys retained a microstrabismus with misalignments averaging 6.9 degrees of exotropia." (PMID 32681083, 2020). "The common pattern of change in eye alignment over time after sustained IGF-1 or GDNF treatment was a slight decrease in exotropia in the first two weeks followed by maintenance of misalignment for the duration of treatment." (PMID 32681083, 2020).
focal epilepsy (1 paper, 2023). A seizure caused by a localized disorder. "Levels of lacrimal and serum GDNF, serum BDNF, and cortisol were not significantly different between the groups of patients with focal epilepsy of different etiologies." (PMID 38069144, 2023).
Fraser syndrome (1 paper, 2017). Fraser syndrome is a rare clinical entity including as main characteristics cryptophthalmos and syndactyly. "Of the candidate genes, four genes (i.e., ITGA8, GRIP1, FREM1, and FREM2) were Fraser syndrome-related genes, encoding proteins that functionally converged on the glial cell-derived neurotrophic factor/RET/bone morphogenic protein (BMP) signaling pathways." (PMID 29197384, 2017).
gastroparesis (1 paper, 2024). Paralysis of the muscles of the stomach wall resulting in delayed emptying of the gastric contents into the small intestine. "The first study found that GES in the setting of gastroparesis was found to decrease ICC, 5-HT2B receptor expression, 5-HT levels, nNOS neurons, CHAT neurons, and GDNF protein expression, which are all implicated in the disease progression." (PMID 39116099, 2024).
glomerulosclerosis (1 paper, 2013). A hardening of the kidney glomerulus caused by scarring of the blood vessels. "Both obese GDNF HET and WT mice demonstrated the renal structural changes that are typical of the obese condition including glomerulomegaly, glomerulosclerosis, interstitial expansion, and inflammation." (PMID 24019901, 2013).
Hepatitis (1 paper, 2012). Inflammation of the liver. "Focal pancreatic ADM, PanINs, myocarditis, and hepatitis were identified histologically in HIRmAb-GDNF-treated monkeys." (PMID 22745701, 2012).
Hernia (1 paper, 2024). "In contrast, hippocampal tissue GDNF concentrations did not exhibit a significant change in rats that underwent a 48‐h period of postsurgical sleep deprivation following hernia repair compared with surgical rats without sleep deprivation." (PMID 39639706, 2024).
Hydroureter (1 paper, 2010). The distention of the ureter with urine. "However, in the absence of SPRY1, mice lacking GDNF or RET make a normal UB that develops into a normal ureter connected to the bladder, as indicated by the absence of hydroureter." (PMID 20084103, 2010).
hyperparathyroidism (1 paper, 2018). Hyperfunction of the parathyroid glands resulting in the overproduction of parathyroid hormone. "Given the key role of the GDNF and RET interaction in kidney and urinary tract development, we also analyzed and found RET G691S/S904S polymorphism in this patient, but additional studies are required to explore the exact mechanism of the RET gene in MSK with hyperparathyroidism." (PMID 29983117, 2018).
Hypovitaminosis (1 paper, 2023). "Hypovitaminosis D‐induced decline in GDNF can apparently modify the well‐ordered development of the dopaminergic pathways." (PMID 36630182, 2023).
intervertebral disc degeneration (1 paper, 2025). "To investigate the regulation of GDNF during intervertebral disc degeneration and its potential contribution to associated pain, we analyzed its expression in disc tissues." (PMID 40012719, 2025). "We demonstrate that the Sox9 regulation of β‐catenin, CCL2, and GDNF constitutes a pivotal mechanism in pain signaling, suggesting that modulation of this pathway may represent a promising therapeutic strategy for intervertebral disc degeneration and its concomitant pain." (PMID 40012719, 2025).
lipoma (1 paper, 2015). A benign, usually painless, well-circumscribed lipomatous tumor composed of adipose tissue. "Furthermore, staining of adipose tissue, lipoma, WDLS, MLS, DDLS, or PLS samples taken from one patient with SPIN1, GNDF, RETph, or MAZ antibody showed that also in individual patients high levels of SPIN1 correlate with high levels of GDNF, RETph, or MAZ." (PMID 25749382, 2015).
liver disease (1 paper, 2022). "In the present study, we assessed GDNF along with biochemical and histological parameters of liver disease in CHB patients." (PMID 35855954, 2022). "However, the clinical use of GDNF in liver disease remains unclear." (PMID 35855954, 2022).
lupus nephritis (1 paper, 2024). Glomerulonephritis in the context of systemic lupus erythematosus. "The lack of differences in the GDNF levels shown in this study can be explained by the absence of patients with lupus nephritis in the sample as they were excluded from this study." (PMID 39459605, 2024). "Elevated GDNF levels have been found in lupus nephritis but not in SLE without renal complications." (PMID 39459605, 2024).
malignant brain gliomas (1 paper, 2021). "Glial cell line-derived neurotrophic factor (GDNF) is a proliferation factor that contributes to the development of malignant brain gliomas in the rat brain." (PMID 33009578, 2021).